ANKK1 (ankyrin repeat and kinase domain containing 1)
Diseases named in the same sentence as ANKK1 in open-access papers (continued):
Sharing a sentence is not in itself a finding about the gene and the disease.
post-traumatic stress disorder (2 papers, 2017 to 2023). An anxiety disorder precipitated by an experience of intense fear or horror while exposed to a traumatic (especially life-threatening) event. "Previous studies have suggested that the DRD2/ANKK1 rs1800497 C > T polymorphism plays a critical role in the risk of post-traumatic stress disorder (PTSD)." (PMID 37274216, 2023). "Further analyses revealed that this patient subset had high rates of post-traumatic stress disorder (PTSD), and enrichment in several distinct genetic polymorphisms associated with cellular responses to stress and DNA damage (PARP1), and in striatal dopamine processing (ANKK1, COMT, DRD2)." (PMID 28257413, 2017).
alexithymia (1 paper, 2024). An agnosia that is a deficiency in understanding, processing, or describing emotions. "In particular, the A1+ allele of the DRD2/ANKK1 TaqI A SNP (rs1800497) is related to alexithymia, and prior emotional abuse leads to a higher risk of alcohol problems." (PMID 39202385, 2024). "First, the A1+ allele of the DRD2/ANKK1 gene is statistically linked to alexithymia." (PMID 39202385, 2024). "The main candidate genes associated with alexithymia are from the serotoninergic pathway (SLC6A4, HTR1A and HTR2A) and neurotransmitter metabolism (DRD2/ANKK1, COMT, BDNF, and OXTR)." (PMID 39202385, 2024).
attention deficit-hyperactivity disorder (1 paper, 2019). A disorder characterized by a marked pattern of inattention and/or hyperactivity-impulsivity that is inconsistent with developmental level and clearly interferes with functioning in at least two settings (e.g. at home and at school). "In the metanalysis of genetic studies related to the group of patients with attention deficit hyperactivity disorder, it was indicated that there is a strong connection of this group of disorders with the ANKK1 TaqI A1 allele." (PMID 31357601, 2019).
cognitive decline (1 paper, 2021). "PD patients who carry ANKK1 rare SNVs showed significant variability in main clinical symptoms, motor complications, and cognitive decline, with limited phenotype/genotype correlation, and the age of onset was from early to classical onset." (PMID 33972609, 2021).
Cognitive impairment (1 paper, 2019). Abnormal cognition is characterized by deficits in thinking, reasoning, or remembering. "SNPs in both catechol-O-methyltransferase (COMT) and ankyrin repeat and kinase domain-containing 1 (ANKK1) have been associated with a variety of cognitive impairments after predominantly mTBI, but this association is less clear in sTBI." (PMID 31105646, 2019).
dementia (1 paper, 2018). Loss of intellectual abilities interfering with an individual's social and occupational functions. "To address these possibilities, we explored the interaction between the DRD2/ANKK1 Taq1A polymorphism and age on caudate volume in a large sample of older adults without dementia (n = 387)." (PMID 29564530, 2018). "We examined the effect of the Taq1A polymorphism of the DRD2/ANKK1 gene on caudate structure and cognitive performance in older adults without dementia." (PMID 29564530, 2018).
diabetes (1 paper, 2016). "Distribution of DRD2/ANKK1 genotype in diabetes group, ACE and PGC1A genotypes in control group (P < 0.01, 0.005, and 0.05, respectively), and all three genetic loci in the total sample (P < 0.05) was significantly different from the expectations of HWE." (PMID 26846149, 2016).
Dyskinesia (1 paper, 2017). A movement disorder which consists of effects including diminished voluntary movements and the presence of involuntary movements. "In American (AMR) population, Brazilians constituted four studies determining rs4704559 (HOMER1), rs2298383 (ADORA2A), rs1800497 (ANKK1) associated with dyskinesia, rs3761422 (ADORA2A) with motor fluctuation and rs28363170 (DAT1) with hallucination." (PMID 28927418, 2017).
heroin dependence (1 paper, 2013). Physical and psychological dependence on the drug heroin. "Based on these results we hypothesized that it is rather a DRD2 than an ANKK1 gene variant which has a direct effect on heroin dependence." (PMID 23840506, 2013). "According to the data the minor (T) allele containing genotypes (TT+CT) of TaqIA polymorphism (rs1800497) in the ANKK1 gene were overrepresented in patients (6.1%+34%) when compared to the controls (3.2%+27.9%) suggesting a genetic effect of the T allele on heroin dependence risk (p = 0.009)." (PMID 23840506, 2013). "Here we present a nominally significant association between the ANKK1 TaqIA SNP and heroin dependence (p = 0.009) which was no longer valid after the stringent Bonferroni correction of multiple testing." (PMID 23840506, 2013).
lung squamous cell carcinoma (1 paper, 2022). "Two variations, S670G in ANK repeat 10 and R736L in repeat 12 has been reported for Gly13 position in ANKK1, with R736L being a somatic mutation associated with lung squamous cell carcinoma." (PMID 35056738, 2022).
muscular dystrophies (1 paper, 2018). "Given that ANKK1 is found in muscle precursors during development and adulthood, we aimed to investigate the expression of ANKK1 in clinical samples of muscular dystrophies." (PMID 29758057, 2018).
neuroblastoma (1 paper, 2024). Neuroblastoma (NB) is the most common solid, extracranial childhood tumor. "In SH-SY5Y neuroblastoma models, we show that ANKK1 interacts with the synapse protein FERM ARH/RhoGEF and Pleckstrin Domain 1 (FARP1), which is a guanine nucleotide exchange factor (GEF) of the RhoGTPases RAC1 and RhoA." (PMID 39409035, 2024). "In the neuroblastoma cells SH-SY5Y, co-IP of endogenous ANKK1 and FARP1 demonstrated their interaction under proliferative (neuroblast-like) or serum-starved conditions (0% fetal bovine serum, FBS) that induce neural differentiation (neuronal-like)." (PMID 39409035, 2024).
rhabdomyosarcoma (1 paper, 2018). A rare aggressive malignant mesenchymal neoplasm arising from skeletal muscle. "The study of ANKK1 proteins during myogenic differentiation of human rhabdomyosarcoma (RD) cell line also shows a decrease in the nuclear signal (D0-D3, t: 6.137, p <0.0001; D0-D6, t: 8.620, p <0.0001; D3-D6, t: 2.591, p = 0.0179)." (PMID 29758057, 2018). "Here, we found an equivalent ANKK1 expression pattern in mice and human myogenic cell lines (C2C12 and rhabdomyosarcoma)." (PMID 29758057, 2018).
substance dependence (1 paper, 2018). The psychological or physiological need to take a substance in order to experience its effects or to avoid the effects of its absence. "Additionally, several single nucleotide polymorphisms (SNPs) in the Ankyrin Repeat and Kinase Domain Containing 1 (ANKK1) and Dopamine Receptor D2 (DRD2) genes which are associated with substance dependence have also been found to be associated with ever tanning." (PMID 29649967, 2018).
psychiatric disorder (5 papers, 2015 to 2024). A disorder characterized by behavioral and/or psychological abnormalities, often accompanied by physical symptoms. "In conclusion, here we provide the first evidence for the precise function of ANKK1 and a biological correlate to the wide range of behavioral phenotypes and psychiatric disorders associated with the ANKK1 TaqIA SNV." (PMID 39409035, 2024). "The rs1800497 SNP of ANKK1, also known as the TaqIA polymorphism, was widely studied among individuals with psychiatric disorders." (PMID 35629112, 2022). "A large number of individual genetic association studies have found that the TaqIA SNP in ANKK1 is linked to psychiatric disorders." (PMID 32383805, 2020). "The exact role of SNP rs2734849 in ANKK1 in psychiatric disorders and drug‐induced side effects has yet to be fully characterized." (PMID 32383805, 2020). "This question is particularly coined by the observations that unfavorable genotypes associated with psychiatric disorders such as Val-allele of COMT and DRD2/ANKK1 A1-allele are selected in some human ethnic groups." (PMID 26136653, 2015). "Despite a large number of studies of TaqIA in addictions and other psychiatric disorders, there is difficulty in interpreting this genetic phenomenon due to the lack of knowledge about ANKK1 function." (PMID 39409035, 2024).
cancer (2 papers, 2012 to 2025). A tumor composed of atypical neoplastic, often pleomorphic cells that invade other tissues. "The increased expression of the ANKK1 gene indicates it may enhance HRMCs’ sensitivity to sorafenib, consistent with other cancer models where higher ANKK1 gene and protein levels are linked to improved drug responses." (PMID 41008631, 2025).
ANKK1 also shares sentences with these, for which no sentence is quoted: alcoholism (5 papers); alcohol use disorder (2); eating disorder (2); Tourette syndrome (2); adenoma (1); behavior disorders (1); bipolar disorder (1); Crohn disease (1); exercise (1); gall-bladder cancer (1); hyperprolactinemia (1); hypertriglyceridemia (1); lung carcinoma (1); mental disorder (1); mood disorder (1); non-Hodgkin lymphoma (1); stress-related disorder (1); traumatic stress disorder (1); type-2 diabetes (1).